LACTB (lactamase beta)
Description:
Mitochondrial serine protease that acts as a regulator of mitochondrial lipid metabolism. Acts by decreasing protein levels of PISD, a mitochondrial enzyme that converts phosphatidylserine (PtdSer) to phosphatidylethanolamine (PtdEtn), thereby affecting mitochondrial lipid metabolism. It is unclear whether it acts directly by mediating proteolysis of PISD or by mediating proteolysis of another lipid metabolism protein. Acts as a tumor suppressor that has the ability to inhibit proliferation of multiple types of breast cancer cells: probably by promoting decreased levels of PISD, thereby affecting mitochondrial lipid metabolism.
Synonyms: MRPL56; FLJ14902; G24
Tractability: Small molecule: it belongs to a druggable protein family. PROTAC: ubiquitination databases record sites on it; its protein half-life has been measured.
Gene: Protein-coding gene on chromosome 15 (63,121,833 to 63,142,061, forward strand). Ensembl gene ENSG00000103642.
Subcellular location: Mitochondrion
Subcellular location (Human Protein Atlas): Mitochondria; Cytosol; Mitotic chromosome; Nuclear membrane
Gene Ontology:
Molecular function: peptidase activity; protein binding; identical protein binding
Biological process: proteolysis; regulation of lipid metabolic process
Cellular component: mitochondrion
Genetic constraint (gnomAD): Loss-of-function variants: 28 observed, 36.66 expected, observed/expected ratio (o/e) 0.76, 90% interval 0.56 to 1.05. The upper end of that interval is the gene's LOEUF score, 1.05, which puts it in group 4 of 6, group 1 being the genes least tolerant of losing a copy. Missense variants: 630 observed, 610.72 expected, observed/expected ratio (o/e) 1.03, 90% interval 0.96 to 1.1. Synonymous variants: 247 observed, 226.76 expected, observed/expected ratio (o/e) 1.09, 90% interval 0.98 to 1.21.
Homologues: Orthologues: chimpanzee LACTB (99% identical), macaque LACTB (98% identical), rabbit LACTB (92% identical), pig LACTB (91% identical), dog LACTB (90% identical), mouse Lactb (88% identical), rat Lactb (87% identical), guinea pig LACTB (85% identical), tropical clawed frog lactb (52% identical), zebrafish lactb (51% identical), Caenorhabditis elegans lact-9 (27% identical). Paralogues in human: LACTBL1 (17% identical).
Diseases named in the same sentence as LACTB in open-access papers:
LACTB is named in the same sentence as 30 diseases in open-access papers, as found by Europe PMC text mining. Sharing a sentence is not in itself a finding about the gene and the disease. The quoted sentences say what the papers report.
breast carcinoma (17 papers, 2017 to 2025). "Research indicates that the expression of LACTB is downregulated in breast cancer, and this downregulation is associated with poor prognosis in breast cancer patients." (PMID 39941048, 2025). "This was followed by our study showing that LACTB’s ability to promote loss of tumorigenicity and onset of differentiation in breast cancer cells is partly dependent on its ability to reprogram the lipid metabolism." (PMID 36375842, 2023). "Decreased LACTB expression is associated with poor clinical outcomes in cancers such as breast cancer, lung cancer, and colorectal cancer, while specific mutations and regulatory mechanisms have been linked to its oncogenic activity in osteosarcoma and pancreatic adenocarcinoma." (PMID 39941048, 2025). "LACTB expression is downregulated in breast cancer and associated with malignancies;Knockdown of miR-374a suppresses the cell proliferative and colony-formation activity as well as migration and invasion capacity in vitro, and LACTB silencing reverses this change." (PMID 36078157, 2022). "Moreover, downregulated LACTB was significantly associated with poor clinical prognosis of breast cancer by TMA analysis." (PMID 29790671, 2018). "LACTB has been reported to be a tumor suppressor, and decreased expression of LACTB has been observed in various cancers, including breast cancer, colon cancer, glioma, ovarian cancer and liver cancer." (PMID 40286848, 2025). "In breast cancer, however, LACTB expression effectively induces G1 phase arrest, which is linked to increased mitochondrial ROS production, leading to caspase-independent cell death." (PMID 39941048, 2025). "In breast cancer, LACTB induces caspase-independent apoptosis by generating ROS, causing DNA damage, and activating pro-apoptotic proteins such as Puma, Bim, and Bax." (PMID 39941048, 2025). "Studies have shown that LACTB plays an important role in inhibiting liver cancer, breast cancer, bladder cancer, and colorectal cancer, and downregulation of LACTB expression often indicates poor prognosis." (PMID 38384969, 2024). "In order to uncover the mechanism of LACTB’s tumor suppressive effects we induced doxycycline inducible LACTB in a panel of normal and breast cancer cell lines and monitored their growth for 6 days." (PMID 36282364, 2023). "In this assay, we examined the protein cell lysate from MCF7ras breast cancer cells with different time points of LACTB induction (6 h, 1 day, 3 days, 6 days)." (PMID 36282364, 2023). "This suggests that in breast cancer LACTB predominantly acts through caspase-independent cell death mechanisms." (PMID 36282364, 2023). "Our work, which studies the detailed mechanisms involved in LACTB-mediated tumour suppression in breast cancer, confirmed and further extended these studies." (PMID 36282364, 2023). "Because our previous work in breast cancer model showed that LACTB modulates the stemness of breast cancer cells, we decided to examine the impact of LACTB expression on ovarian cancer stem cell properties." (PMID 36375842, 2023). "In breast cancer, the differentiation-inducing mechanism was shown to be triggered by LACTB-induced changes in lipid metabolism and the resulting changes in the levels of mitochondrial phosphatidylethanolamines and lysophosphatidyltheanolamines." (PMID 36282364, 2023). "Herein, we described the more detailed mechanism by which LACTB suppresses tumorigenesis and induces cancer cell death in breast cancer." (PMID 36282364, 2023). "A different manifestation of LACTB’s function was uncovered by the discovery that LACTB acts as a tumour suppressor in breast cancer cells." (PMID 35626737, 2022). "In line with the original findings in breast cancer cells, a study employing breast cancer tissue microarrays demonstrated that LACTB downregulation correlated with poor clinical outcome." (PMID 35626737, 2022).
breast carcinoma (continued). "Following the discovery that LACTB exerts a tumour suppressive effect in breast cancer cells, the expression level of LACTB and its effect on the cancer cell phenotype have been reported for several other cancer forms." (PMID 35626737, 2022). "More recently, it was reported that LACTB is a tumor suppressor that inhibits the proliferation and promotes the apoptosis of breast cancer cells." (PMID 33507917, 2021). "LACTB, by acting on mitochondrial lipid metabolism leads to increased differentiation and reduced proliferation of breast cancer cells." (PMID 28798698, 2017). "Analysis of LACTB protein level in 18 breast cancer cell lines revealed that LACTB expression was downregulated (but never completely absent) in 15 of the 18 cell lines tested." (PMID 28785375, 2017). "Moreover, overexpression of LACTB suppresses breast cancer cell proliferation, migration, and invasion, while inducing caspase-independent cell death pathways, thereby inhibiting cancer progression." (PMID 39941048, 2025). "However, the complexity of cellular answers to LACTB is manifested by the fact that other cellular models within breast cancer category are reacting differently to LACTB." (PMID 36282364, 2023). "In order to find out whether induction of ROS in our panel of breast cancer cell lines is the major mode of LACTB induced cell death we used antioxidants to prevent the DNA damage." (PMID 36282364, 2023). "In order to have a better perspective of LACTB-mediated apoptosis in breast cancer, we examined whether LACTB induction under a more physiological 3D culturing conditions leads to changes in cellular signaling similar to that of 2D cultivation." (PMID 36282364, 2023). "In contrast to LACTB induction, the treatment of a panel of breast cancer cell lines (MCF7ras, HCC1806, Hs578t) with Actinomycin D resulted in PARP degradation and caspase cleavage in all or some of our tested cell lines (caspase 7, 8 9) confirming the onset of caspase-dependent apoptosis." (PMID 36282364, 2023). "Moreover, LACTB has exhibited an inhibitory role in breast cancer (BRCA) cellular proliferation via regulating the accumulation of the PE/LPE lipid species." (PMID 36078157, 2022). "While the direct mechanism for tumor suppression by LACTB is unknown, studies have shown that LACTB expression results in reduced PISD protein levels in human breast cancer cells." (PMID 36534696, 2022). "LACTB expression is downregulated by miR-374a, promoting cancer progression in breast cancer." (PMID 36078157, 2022). "A somewhat different conclusion was drawn from studies of phospholipid metabolism in breast cancer cells, where it was demonstrated that increased LACTB expression leads to a diminished synthesis of the membrane lipid PE from PS through deactivation of the enzyme PISD." (PMID 35626737, 2022). "In human breast cancer cell lines, expression of the mitochondrial protein lactamase beta (LACTB) is significantly downregulated; LACTB downregulation is required for the synthesis of two phospholipids, phosphatidyl ethanolamine (PE) and LysoPE, that are essential for membrane biosynthesis." (PMID 29739810, 2018). "Interestingly, HS578t cells were also reported to have very low levels of caspase 3, compared with other breast cancer cell lines, what might explain the preferential activation of the caspase-independent processes upon LACTB induction." (PMID 36282364, 2023). "Recent studies identified miRNAs such as miR-373-5p and miR-1276 in colorectal cancer and miR-374a in breast cancer, which bind to the 3′-UTR of LACTB mRNA, suppressing its translation, reducing protein levels, and impairing its tumor-suppressive functions." (PMID 39941048, 2025). "We confirmed these observations by FACS analysis examining the cell cycle progression of breast cancer cells with and without LACTB expression at different time points." (PMID 36282364, 2023).
breast carcinoma (continued). "In line with this, LACTB was downregulated in several neoplastic cells compared with non-tumorigenic cells, and furthermore, LACTB was reduced in 34–42% of breast cancers, whilst present in 100% of normal mammary glands." (PMID 28642719, 2017). "Although the MCF7-RAS breast cancer line showed LACTB levels similar to that in nontumorigenic cell lines, this cell line was found to have a R469K mutation in the LACTB gene." (PMID 28785375, 2017). "The growth rate of all breast cancer cell lines tested was negatively affected by the induction of LACTB expression while no significant changes were observed in the control non-tumorigenic HME cell line after LACTB induction." (PMID 36282364, 2023). "In this regard, LACTB was shown to mediate tumour suppression through PI3K/AKT/mTOR in colorectal cancer, inhibiting Hippo pathway in melanoma, modulating lipid metabolism in breast cancer and hepatocellular carcinoma and regulating autophagy in gastric cancer." (PMID 36282364, 2023). "However, the reduction in PE synthesis induced by LACTB expression was observed exclusively in breast cancer cell lines and not in the corresponding non-tumorigenic mammary cell lines." (PMID 35626737, 2022).
colorectal cancer (12 papers, 2021 to 2025). A primary or metastatic malignant neoplasm that affects the colon or rectum. "Studies focusing on LACTB regulation in colorectal cancer reveal that microRNAs (miRNAs) such as miR-373-5p and miR-1276 mediate a significant reduction in LACTB expression." (PMID 39941048, 2025). "Further research in colorectal cancer has shown that LACTB regulates the expression of Twist1, a transcription factor for mesenchymal stem cell markers, in a PI3K pathway-dependent manner, inhibiting EMT progression." (PMID 39941048, 2025). "Treatment with the DNA methyltransferase inhibitor 5-Aza-dC restores LACTB expression in colorectal cancer cells, demonstrating the reversibility of this epigenetic modification." (PMID 39941048, 2025). "Conversely, in colorectal cancer, LACTB activates autophagy by inhibiting the PI3K/AKT/mTOR pathway then suppressing cell proliferation." (PMID 39941048, 2025). "Due to the functional significance of colorectal cancer, research on LACTB in relation to colorectal cancer has become a key focus in LACTB studies." (PMID 39941048, 2025). "Previous investigations have demonstrated that LACTB is notably downregulated in several types of cancer, including hepatocellular carcinoma, breast cancer, colorectal cancer, glioma, and melanoma." (PMID 38149985, 2023). "In colorectal cancer cells, upregulation of LACTB expression can inhibit the cellular EMT process and increase the expression of epithelial markers through the autophagy signaling pathway involving PI3K/AKT/mTOR." (PMID 38149985, 2023). "Following studies extended the tumor suppressive role of LACTB to different cancer tissues such as colorectal cancer, glioma, gastric cancer, and melanoma." (PMID 36375842, 2023). "In colorectal cancer, it was shown that LACTB inhibits EMT and proliferation through PI3K inactivation, and the use of PI3K inhibitors was suggested as a possible therapeutic intervention." (PMID 36375842, 2023). "In colorectal cancer, low LACTB expression level correlated with a poor clinical outcome, and an overexpression of LACTB in colon cancer cells suppressed proliferation, invasion and epithelial-to-mesenchymal transition." (PMID 35626737, 2022). "Conversely, increased LACTB expression suppresses colorectal cancer onset and progression." (PMID 39941048, 2025). "In breast and colorectal cancers, microRNAs mainly negatively regulate the expression of LACTB." (PMID 38149985, 2023). "In breast and colorectal cancers, low expression of LACTB predicts a poorer prognosis for patients." (PMID 37937197, 2023). "Silencing LACTB promotes the viability, migration, and invasiveness in colorectal cancer cells;Silencing LACTB partially abolishes the apoptotic effect of pinocembrin on colorectal cancer cells." (PMID 36078157, 2022). "LACTB expression in colorectal cancer tissue samples is lower than that in nonmalignant tissue samples;LACTB inhibits cell invasion, migration, and proliferation by promoting autophagy in vitro;LACTB modulates tumorigenesis in vivo." (PMID 36078157, 2022).
hepatocellular carcinoma (10 papers, 2021 to 2025). A malignant tumor that arises from hepatocytes. "Studies on hepatocellular carcinoma tissue samples reveal significantly reduced LACTB expression compared to normal tissues, a decrease frequently linked to poor prognosis." (PMID 39941048, 2025). "In hepatocellular carcinoma cells, LACTB expression and functional regulation are abnormally altered compared to normal tissues." (PMID 39941048, 2025). "In summary, proper functioning of LACTB plays a crucial role in suppressing hepatocellular carcinoma progression." (PMID 39941048, 2025). "Overexpression of LACTB in hepatocellular carcinoma cells and patient-derived xenograft models significantly inhibited cell viability, colony formation, and tumor growth." (PMID 39941048, 2025). "This modification suppresses the proteolytic activity of LACTB, leading to enhanced mitochondrial function and promoting hepatocellular carcinoma cell growth." (PMID 39941048, 2025). "In some hepatocellular carcinoma patients, LACTB expression remains unchanged but undergoes succinylation at the K284 site by oxoglutarate carrier 1 (OXCT1)." (PMID 39941048, 2025). "It promotes succinylation of Lactamase Beta (LACTB)-K284, thereby blocking its catabolic activity and enhancing mitochondrial respiration, which facilitates hepatocellular carcinoma growth." (PMID 39857793, 2025). "Furthermore, succinylation at LACTB K284 is also correlated with poor prognosis in hepatocellular carcinoma patients." (PMID 39941048, 2025). "Likewise, a low expression level of LACTB correlated with a poor prognosis in hepatocellular carcinoma and overexpression of LACTB in hepatocellular carcinoma cells resulted in the inhibition of proliferation, migration and invasion." (PMID 35626737, 2022). "In glioblastoma, KAT2A/α-KGDH complex-driven histone H3 succinylation at K79 activates oncogenic transcription, while in hepatocellular carcinoma, OXCT1-succinylated LACTB reinforces mitochondrial metabolism to support tumor progression." (PMID 41383634, 2025). "In hepatocellular carcinoma (HCC), OXCT1 functions as a lysine Succinyl transferase, modifying LACTB at lysine 284 to enhance mitochondrial membrane potential and support tumor growth." (PMID 40931345, 2025). "Additionally, a study in hepatocellular carcinoma revealed that succinylation at the K284 residue of LACTB enhances mitochondrial function without altering its protein levels." (PMID 39941048, 2025).
Obesity (8 papers, 2017 to 2022). Accumulation of substantial excess body fat. "Dysregulation of LACTB is associated with obesity and atherosclerosis potentially due to its involvement in metabolic pathways, in particular, the phospholipid metabolism in mitochondria." (PMID 36534696, 2022). "The causative link between LACTB and obesity has been detected by data integration and validated in the transgenic mice; i.e., LACTB overexpression results in obesity phenotype." (PMID 36078157, 2022). "Given its strong relation to metabolic pathways, LACTB is also validated as an obesity gene capable of modifying adiposity." (PMID 36534696, 2022). "In these untargeted studies, LACTB was identified together with ZFP90 and Lpl as a causative factor for obesity-related traits." (PMID 35626737, 2022). "Further molecular studies at the protein level are, however, required to determine the function of ORMDL3 and LACTB in connection with obesity." (PMID 29666371, 2018). "Although the function of LACTB in adipose has not been fully elucidated, these studies suggest that a reduction in LACTB function and, in turn, an increase in butanoate metabolism and decrease of succinylcarnitine levels are beneficial for obesity treatment." (PMID 29666371, 2018). "Previous studies have suggested a role for LACTB in obesity and mitochondrial membrane organization." (PMID 28642719, 2017). "Pharmacological modulation of LACTB function could also prove useful for targeting alterations in metabolic disorders due to the link to obesity." (PMID 28642719, 2017). "Another interesting feature is that LACTB is a bona fide obesity gene." (PMID 28785375, 2017).